PDPK1 (3-phosphoinositide dependent protein kinase 1)
Description:
Serine/threonine kinase which acts as a master kinase, phosphorylating and activating a subgroup of the AGC family of protein kinases. Its targets include: protein kinase B (PKB/AKT1, PKB/AKT2, PKB/AKT3), p70 ribosomal protein S6 kinase (RPS6KB1), p90 ribosomal protein S6 kinase (RPS6KA1, RPS6KA2 and RPS6KA3), cyclic AMP-dependent protein kinase (PRKACA), protein kinase C (PRKCD and PRKCZ), serum and glucocorticoid-inducible kinase (SGK1, SGK2 and SGK3), p21-activated kinase-1 (PAK1), TSSK3, protein kinase PKN (PKN1 and PKN2). Plays a central role in the transduction of signals from insulin by providing the activating phosphorylation to PKB/AKT1, thus propagating the signal to downstream targets controlling cell proliferation and survival, as well as glucose and amino acid uptake and storage. Negatively regulates the TGF-beta-induced signaling by: modulating the association of SMAD3 and SMAD7 with TGF-beta receptor, phosphorylating SMAD2, SMAD3, SMAD4 and SMAD7, preventing the nuclear translocation of SMAD3 and SMAD4 and the translocation of SMAD7 from the nucleus to the cytoplasm in response to TGF-beta. Activates PPARG transcriptional activity and promotes adipocyte differentiation (By similarity). Activates the NF-kappa-B pathway via phosphorylation of IKKB. The tyrosine phosphorylated form is crucial for the regulation of focal adhesions by angiotensin II. Controls proliferation, survival, and growth of developing pancreatic cells (By similarity). Participates in the regulation of Ca(2+) entry and Ca(2+)-activated K(+) channels of mast cells (By similarity). Essential for the motility of vascular endothelial cells (ECs) and is involved in the regulation of their chemotaxis. Plays a critical role in cardiac homeostasis by serving as a dual effector for cell survival and beta-adrenergic response (By similarity). Plays an important role during thymocyte development by regulating the expression of key nutrient receptors on the surface of pre-T cells and mediating Notch-induced cell growth and proliferative responses (By similarity). Provides negative feedback inhibition to toll-like receptor-mediated NF-kappa-B activation in macrophages (By similarity). [Isoform 3]: Catalytically inactive.
Synonyms: PDK1; PRO0461
Tractability: Small molecule: a drug acting on it is in phase 2 or 3 trials; a structure with a bound ligand is known; a high-quality ligand is known; it has a high-quality binding pocket; it belongs to a druggable protein family. Antibody: its Gene Ontology location is reachable by antibodies, with high confidence; UniProt places it where antibodies can reach, with medium confidence. PROTAC: UniProt records ubiquitination sites on it; ubiquitination databases record sites on it; its protein half-life has been measured; a small molecule that binds it is known.
Target class: Enzyme; Protein Kinase; AGC protein kinase group; Kinase; AGC protein kinase PDK1 subfamily
Chemical probes: GSK2334470 (high quality), GSK2375584A, PD005768, PD080943, PD083388, PD083917
Safety:
Unwanted effects reported when the protein is acted on. In parentheses: how it was acted on, where the effect was seen, and who reports it.
heart disease (cardiovascular system; source: Force et al. (2011))
Gene: Protein-coding gene on chromosome 16 (2,537,978 to 2,603,190, forward strand). Ensembl gene ENSG00000140992.
Subcellular location: Cytoplasm; Nucleus; Cell membrane; Cell junction, focal adhesion
Subcellular location (Human Protein Atlas): Cytosol; Primary cilium tip
Pathways (Reactome):
Signal Transduction: Activation of AKT2; Estrogen-stimulated signaling through PRKCZ; G beta:gamma signalling through PI3Kgamma; Integrin signaling; PIP3 activates AKT signaling; RHO GTPases activate PKNs; VEGFR2 mediated cell proliferation; VEGFR2 mediated vascular permeability
Immune System: CD28 dependent PI3K/Akt signaling; CLEC7A (Dectin-1) signaling; Downstream TCR signaling; FCERI mediated NF-kB activation; Role of LAT2/NTAL/LAB on calcium mobilization
Disease: Constitutive Signaling by AKT1 E17K in Cancer; SARS-CoV-1 targets host intracellular signalling and regulatory pathways; SARS-CoV-2 targets host intracellular signalling and regulatory pathways
Cellular responses to stimuli: High laminar flow shear stress activates signaling by PIEZO1 and PECAM1:CDH5:KDR in endothelial cells
Hemostasis: GPVI-mediated activation cascade
Neuronal System: RSK activation
Gene Ontology:
Molecular function: 3-phosphoinositide-dependent protein kinase activity; phospholipase activator activity; phospholipase binding; protein binding; protein serine kinase activity; protein serine/threonine kinase activity; ATP binding; protein kinase activity
Biological process: calcium-mediated signaling; cell migration; cellular response to epidermal growth factor stimulus; cellular response to insulin stimulus; epidermal growth factor receptor signaling pathway; extrinsic apoptotic signaling pathway; intracellular signal transduction; intracellular signaling cassette; negative regulation of endothelial cell apoptotic process; negative regulation of transforming growth factor beta receptor signaling pathway; phosphatidylinositol 3-kinase/protein kinase B signal transduction; positive regulation of angiogenesis; positive regulation of blood vessel endothelial cell migration; positive regulation of phosphatidylinositol 3-kinase/protein kinase B signal transduction; positive regulation of protein localization to plasma membrane; positive regulation of release of sequestered calcium ion into cytosol; positive regulation of sprouting angiogenesis; positive regulation of vascular endothelial cell proliferation; protein phosphorylation; regulation of canonical NF-kappaB signal transduction; actin cytoskeleton organization; insulin receptor signaling pathway; protein autophosphorylation; T cell costimulation; vascular endothelial cell response to laminar fluid shear stress; and 7 more
Cellular component: cytoplasm; cytosol; plasma membrane; plasma membrane bounded cell projection; cytoplasmic vesicle; focal adhesion; nucleus; postsynaptic density
Genetic constraint (gnomAD): Loss-of-function variants: 4 observed, 27.48 expected, observed/expected ratio (o/e) 0.15, 90% interval 0.071 to 0.33. The upper end of that interval is the gene's LOEUF score, 0.33, which puts it in group 1 of 6, group 1 being the genes least tolerant of losing a copy. Missense variants: 159 observed, 251.66 expected, observed/expected ratio (o/e) 0.63, 90% interval 0.55 to 0.72. Synonymous variants: 113 observed, 100.38 expected, observed/expected ratio (o/e) 1.13, 90% interval 0.97 to 1.32.
Homologues: Orthologues: macaque PDPK1 (98% identical), mouse Pdpk1 (94% identical), guinea pig PDPK1 (93% identical), rat Pdpk1 (93% identical), dog PDPK1 (93% identical), pig PDPK1 (92% identical), chimpanzee PDPK1 (91% identical), tropical clawed frog pdpk1 (78% identical), zebrafish pdpk1b (75% identical), zebrafish pdpk1a (73% identical), rabbit PDPK1 (53% identical), Drosophila melanogaster Pdk1 (41% identical), and 1 more. Paralogues in human: AKT3 (25% identical), AKT2 (25% identical), AKT1 (25% identical), PRKCQ (24% identical), PRKCD (23% identical).
Diseases named in the same sentence as PDPK1 in open-access papers:
PDPK1 is named in the same sentence as 79 diseases in open-access papers, as found by Europe PMC text mining. Sharing a sentence is not in itself a finding about the gene and the disease. The quoted sentences say what the papers report.
breast cancer (25 papers, 2014 to 2024). A primary or metastatic malignant neoplasm involving the breast. "Similar findings of PDPK1 promoting tumor initiation in cooperation with Erbb2 or Ras activation have been made in breast cancer cells, or in BRAF V600 mutant melanoma where loss of PDPK1 reduced tumor formation." (PMID 34079928, 2021). "In breast cancer, PDPK1 is highly expressed, which is associated with poor prognosis." (PMID 39624293, 2024). "The risk score of breast cancer patients was calculated using the following formula: Risk score = −0.482 * expression of CPEB1 + 0.468 * expression of NOTCH3 + 0.213 * expression of NUAK1 + 0.321 * expression of PDPK1." (PMID 36072578, 2022). "Similarly, SGK3 was also found to be a key mediator of PDPK1‐dependent melanomagenesis and a driver for tumour formation in breast cancer cells in both PIK3CA wild‐type and mutated cells in an AKT‐independent manner." (PMID 32926495, 2020). "Amplification or overexpression of PDPK1 has been implicated in tumourigenesis and cancer cells survival in many human cancers including breast cancer, oesophageal squamous cell carcinoma, melanoma, gastric carcinoma, hepatocellular carcinoma 55 and acute myeloid leukaemia." (PMID 32926495, 2020). "For example, in breast cancer models the release of EV-associated miR-181c and its entry into endothelial cells downregulates 3-phosphoinositide dependent protein kinase 1 (PDPK1) resulting in disruption of cofilin regulated actin dynamics and local inactivation of BBB." (PMID 30585246, 2018). "Beyond expression data, artificially increasing PDPK1 expression in breast cancer cells promotes cells proliferation and invasion." (PMID 39624293, 2024). "By targeting PDPK1 in brain endothelial cells and disturbing the actin filament localization, ExomiR-181c translocation from breast cancer BC cells facilitates the breakdown of the BBB in vitro." (PMID 38455764, 2024). "BRD4/LSD1/NuRD complex then represses the activation of drug-resistant genes such as WNT4, LRP5, BRAF, GNA13, and PDPK1 in breast cancer cells." (PMID 35740532, 2022). "To date, the role of PDPK1 in driving cancer and chemoresistance has been outlined in multiple cancers, including acute myeloid leukaemia, breast cancer and ovarian cancer." (PMID 32926495, 2020). "Extracellular vesicles (EVs) containing miR-181c disrupt the BBB and promote brain metastasis from breast cancer by downregulating 3-phosphoinositide-dependent protein kinase 1 (PDPK1), and subsequently altering the actin filaments." (PMID 31142339, 2019). "This activates GNA13 and PDPK1 expression leading to drug resistance in breast cancer." (PMID 35740532, 2022). "In addition, the expression levels of CPEB1, NOTCH3, NUAK1, and PDPK1 were significantly discrepant among the molecular subtypes of breast cancer." (PMID 36072578, 2022). "miR-181c could be enriched in brain metastatic breast cancer cell-derived exosomes and target 3-phosphoinositide-dependent protein kinase-1(PDPK1) in endothelial cells." (PMID 36430471, 2022). "Breast cancer cells metastasizing to the brain may indeed promote the destruction of the blood–brain barrier (BBB) through the secretion of EV-associated miR-181c, which in turn down-regulates 3-phosphoinositide-dependent protein kinase-1 (PDPK1)." (PMID 35076579, 2022). "Meanwhile, PDPK1 was regulated by several molecular pathways, including mTORC2/PI3K, and then facilitated the proliferation of breast cancer cells." (PMID 36072578, 2022). "Along with this, PDPK1 proteins phosphorylate the activating segment of AKT, which affects various key cell functions and facilitate the breast cancer progression." (PMID 28871116, 2017). "The roles of PDPK1, PKN2, PPP2R2A, and PPP2R5E in PI3K pathway regulation of HER2+ breast cancer progression and inhibition by PGB-0-ol remain unclear." (PMID 38028209, 2023).
breast cancer (continued). "Moreover, extracellular vesicles from breast cancer cells, containing miR-181c have been found to disrupt the BBB and promote brain metastasis by downregulating 3-phosphoinositide-dependent protein kinase 1 (PDPK1) and altering the actin filaments." (PMID 36009578, 2022). "We reviewed the functional properties of the driver nodes found to have the highest impact in controlling the essential proteins; they are ERBB2, SRC, PDPK1, PRKDC, mTOR for breast cancer, ERBB2, AKT1, GSK3B, ABL1 in pancreatic cancer, and RET in ovarian cancer." (PMID 28871116, 2017). "3-phosphoinositide dependent protein kinase-1 (PDK1), a transducer protein that functions downstream of PI3K, is responsible for the regulation of cell proliferation and migration and it also has been found to play a key role in different cancers, pancreatic and breast cancer amongst others." (PMID 31683659, 2019). "Other genes, including ATP5A, BCR, FGFR4, PDPK1, PIP5K1C, RIOK3, and SRC, also act to regulate TRAIL-induced apoptosis, but their potential to overcome resistance to TRAIL-induced cytotoxicity when inhibited may be more context specific (that is, in a more-restricted subset of breast cancer cells)." (PMID 24745479, 2014).
prostate carcinoma (17 papers, 2013 to 2025). A carcinoma that arises from epithelial cells of the prostate gland. "There are several reports that show that PDPK1 is associated with prostate cancer, neuroinflammation, autophagosome biogenesis, and also GC." (PMID 35302432, 2022). "In prostate cancer, PDPK1 mutations are rare (≤0.2%), yet PDPK1 amplification occurs in up to 8.1% of patients." (PMID 32630372, 2020). "Using a genome-wide lentiviral small hairpin RNA library screen, the PDPK1 inhibitor BX-795 has been shown to significantly reduce tumor-specific cell growth and synergize with docetaxel to enhance treatment sensitivity in prostate cancer cells." (PMID 40002724, 2025). "Many studies now corroborate the conclusion that PDPK1 contributes to the progression of cancers and shows high expression in cancers, such as breast, gastric, and prostate cancer." (PMID 39624293, 2024). "PDPK1, previously shown to have a role in prostate cancer cell survival, also fulfils two of the set criteria." (PMID 37108830, 2023). "Our study showed that PI3K, Akt3, and PDPK1 form a cFFL; all involving in prostate cancer formation." (PMID 25707690, 2015). "The PI3K/PDPK1/AKT pathway is crucial for prostate cancer progression and a recent study showed a reciprocal regulation between the AR and the AKT pathway." (PMID 24913494, 2014). "It has been suggested that n-3 PUFA induces cell apoptosis in prostate cancer via a mechanism of LOX15-mediated SDC-1-dependent suppression of PDPK1/AKT/BAD phosphorylation." (PMID 23762859, 2013). "Furthermore, CPT1A directly binds to SP5 and promotes its succinylation, which in turn enhances SP5's binding to the PDPK1 promoter, thereby increasing PDPK1 transcription and promoting prostate cancer progression." (PMID 40070041, 2025). "In addition, the upregulation of PDPK1 is frequently detected in prostate cancer, esophageal squamous cell cancer, gastric cancer, and acute myeloid leukemia." (PMID 39624293, 2024). "At the molecular level, succinylation of a specific protein, for example, CPT1A, causes succinylation of SP5 at K391, which activates the master signaling pathway PDPK1-AKT/mTOR and promotes proliferation and survival of prostate cancer cells." (PMID 40865948, 2025). "Common genetic alterations within the three prostate cancer datasets analyzed were observed in PTEN, DEPTOR, SGK3, FOXO1/3, MAP3K7, RRAGD, SESN1, PIK3CA, PIK3C2B, and PDPK1." (PMID 32630372, 2020).
lung carcinoma (12 papers, 2013 to 2025). "Further studies have found that KTN1-AS1 regulated the expression of miR-130a-5p target gene PDPK1 in NSCLC cells to inhibit autophagy in lung cancer cells." (PMID 40438586, 2025). "In our study, PDPK1 is related to better prognosis in lung cancer, especially in LUAD, in addition, its autoantibody can be regarded as a sensitive biomarker in predicting bone metastasis." (PMID 39949782, 2025). "Nevertheless, studies demonstrated that PDPK1 was a key regulator in promoting lung cancer progression, thus these contradictory conclusions require more in-depth mechanistic studies." (PMID 39949782, 2025). "BBR can significantly inhibit the growth of lung cancer cells by reducing the protein expression of transcription factors Sp1 and 3-phosphoinositide dependent protein kinase 1 (PDPK1), both of which are related to cancer growth and progression." (PMID 35153781, 2022). "Using the TargetScan website, we further predicted that miR-33a-5p can bind to the 3′UTR region of the PDPK1 gene in lung cancer cells." (PMID 34992655, 2021). "circANXA2 regulates the transcription of the miR-33a-5p downstream target gene PDPK1 and affects the malignant progression of lung cancer." (PMID 34992655, 2021). "circANXA2 further affects downstream PDPK1 expression by regulating miR-33a-5p and thereby affecting the malignancy of the lung cancer cells." (PMID 34992655, 2021). "In the present study, we found that compared with normal lung epithelial cells, miR-33a-5p and PDPK1 expression levels were significantly low and high in a variety of lung cancer cells, respectively." (PMID 34992655, 2021). "Our findings indicated that both miR‐214‐3p and HOTAIR act as upstream regulators of PDPK1 gene expression in the presence of SM in lung cancer cells." (PMID 31475459, 2019). "Herein, we extended these studies and found that SM inhibited the growth of human lung cancer cells by suppressing PDPK1 expression through a reciprocal interaction between HOTAIR and miR‐214‐3p." (PMID 31475459, 2019). "Our findings suggested that SM‐inhibited human lung cancer cell growth via inhibition of the PDPK1 and HOTAIR, and induction of miR‐214‐3p signalling axis." (PMID 31475459, 2019). "These interactions contribute to the inhibition of PDPK1 expression, and, together with a feedback regulatory axis, synergistically enhance the overall anti‐lung cancer effect of SM." (PMID 31475459, 2019). "And knockdown of PDPK1 significantly repressed the growth of lung cancer cells, suggesting that miR‐138 inhibited cell proliferation by targeting PDPK1 in lung cancer cells." (PMID 28840963, 2018). "Despite these findings, the true role and function of PDPK1 in the tumorigenesis, growth and progression of lung cancer still required to be determined." (PMID 28840963, 2018). "Therefore, KTN1-AS1 inhibited autophagy in lung cancer cells through miR-130a-5p/PDPK1 signaling pathway." (PMID 40438586, 2025). "In the present study, PDPK1 expression was upregulated in the lung cancer tissues." (PMID 34992655, 2021). "Immunohistochemical results showed that PDPK1 was highly expressed in the lung cancer tissues." (PMID 34992655, 2021). "Different genes located on the 16p13.3 locus were hypothesized to be implicated in the poor prognosis: in lung cancer TSC2 was brought forward, in pancreatic cancer PDPK1." (PMID 26222184, 2015). "However, the role of PDPK1 in lung cancer is not well understood." (PMID 34992655, 2021). "In addition, SM reduced HOTAIR binding to PDPK1 protein implying that this interaction could lead to a reduction of genes, including PDPK1 that may be involved in the effect of SM in anti‐lung cancer effects." (PMID 31475459, 2019). "Thus, miR‐138 and PDPK1 might predict the prognosis and both together represented promising biomarkers in progression and survival in patients with lung cancer." (PMID 28840963, 2018).
lung carcinoma (continued). "More importantly, our in vivo data were consistent with the findings from that in vitro, confirming the enhanced effect of BBR in the presence of MET on inhibition of lung cancer 8, 60, 61, and regulation of SP1, PDPK1 and DNMT1 expressions." (PMID 28840963, 2018). "Notably, the only lncRNA ENSG00000175701.6 (also known as LINC00116), one ceRNA of PDPK1, in K13M4 was identified as a potential biomarker for lung cancer." (PMID 29340088, 2017). "In an effort to explore the anti-tumor effects of NAC on potential targets, we turned our attention to 3-phosphoinositide-dependent protein kinase 1 (PDK1), a master regulator of signal cascades that are involved in suppression of apoptosis and promotion of tumor growth including lung cancer." (PMID 23867003, 2013).